ALK (ALK receptor tyrosine kinase)
Diseases named in the same sentence as ALK in open-access papers (continued):
Sharing a sentence is not in itself a finding about the gene and the disease.
tumor (continued). "In addition, ALK-positive adenocarcinomas tend to present a more rapid metastases to lymph nodes or distant sites compared with EGFR mutation or with wild type, indicating that the tumor is more aggressive." (PMID 39497711, 2024). "Additionally, we could not find any association between RICTOR amplification and any other genetic drivers (ALK translocation and KRAS mutation status were available in 286 and 15 patients, respectively) or tumor mutational burden." (PMID 38706776, 2024). "In the IMpower010 trial, the difference in OS between atezolizumab and best supportive care (BSC) was more pronounced in patients without EGFR/ALK mutations and with PD-L1 tumor cells ≥ 50% (5-year OS 89.1% with atezolizumab and 77.5% with BSC [HR 0.42 (0.23–0.78)]." (PMID 39590145, 2024). "The tumor harbored neither EGFR gene mutation nor ALK gene rearrangement." (PMID 38800395, 2024). "Moreover, the results obtained in the 3D BC model experiments suggest that MELK and ALK targeting could work also within the tumor and the tumor environment." (PMID 38589728, 2024). "Moreover, eventual positive results could be translated to other tumours expressing ALK, thus expanding the number of patients who could benefit from this treatment." (PMID 38877641, 2024). "Several studies have shown that in NSCLC cells with gene alterations of KRAS G12C, BRAF V600E, EGFR, ALK, or ROS1, dysregulation of the Hippo pathway decreases the initial response to various tyrosine kinase inhibitors, which is associated with resistance of targeted therapy and tumor recurrence." (PMID 38499647, 2024). "No ALK related mutations were detected by circulating tumor DNA sequencing from the plasma sample." (PMID 38978737, 2024). "Inoperable tumours or cases with incomplete resection can be treated with a variety of treatment options, including corticosteroids, non-steroidal anti-inflammatory agents (NSAIDs), radiotherapy, adjuvant chemotherapy or ALK-inhibitors when ALK translocation is present." (PMID 38594735, 2024). "Moreover, tumours with low ALK expression may also be targeted effectively using logic AND gate-based CAR T-cells in which ALK binding was coupled to delivery of an activating signal by a first generation CAR." (PMID 36831514, 2023). "In addition, the subgroup of ALK+ ALCL boasts a unique phenotype in which PD-L1 expression was detected at high rates in the tumor and microenvironment of these lymphomas, although this has not yet been correlated to response rates to PD-1/PD-L1 targeting agents." (PMID 36776886, 2023). "Moreover, our data weakly indicates that an overall higher FN1 expression in an ALK-driven tumor tissue could be correlated with worse survival." (PMID 37511126, 2023). "Nonetheless, considering that ALK inhibitors have proven effective against high-risk ALK-positive NBL, and given that mIBG is taken up by NBL tumor cells via the norepinephrine transporter (NET), combination therapy with mIBG and brigatinib could potentially lead to improved therapeutic outcomes." (PMID 37765282, 2023). "Notably, TPX-0131 effectively halted tumor growth in ALK G1202R and ALK compound mutations, whereas lorlatinib did not exhibit the same level of suppression." (PMID 38274094, 2023). "To understand how the phenotypic heterogeneity of different tumor regions relates to functional differences, we undertook drug profiling of tumor‐derived cultures from four regions, and compared responses to those in patient‐matched normal lung tissue‐derived cells and ALK‐rearranged H3122 cells." (PMID 36423211, 2023). "Additional serum cytokines could also be screened for potential disease monitoring utility, including TGF-β, which has been demonstrated in a preclinical study to have abrogated tumour suppressive response in ALK + tumours, and other serum cytokines reported to be associated with NSCLC." (PMID 37120670, 2023).
tumor (continued). "In November 2020, within the period used to define the COVID-19 cohort for this analysis, the European Medicines Agency approved nivolumab plus ipilimumab with two cycles of chemotherapy for 1L treatment of mNSCLC, in adults whose tumours have no sensitising EGFR mutation or ALK translocations." (PMID 37386452, 2023). "Within the ALK-positive G1, G2, and G3 cases, cytoplasmic and membranous ALK immunoreactivities were observed in 7 (50%) and 7 (50%), 0 (0%) and 3 (100%), and 13 (76.5%) and 4 (23.5%) cases, respectively; the difference between G3 scores and the other tumor grades was statistically significant." (PMID 37592266, 2023). "Therefore, in nude mice transplanted tumors in NCI-H3122 cells, the main mechanism of action of iruplinalkib may be to inhibit ALK phosphorylation, and then inhibit tumor growth by inhibiting the downstream JAK/STAT pathway." (PMID 37036582, 2023). "Among the nine patients with BPM, driver mutations of primary tumours were determined by NGS, including EGFR mutations (5, 55.6%), which include 19del (4, 44.4%), L858R+A871E + MET (1, 11.1%), ALK (1, 11.1%), ROS1 (1, 11.1%), KRAS (1, 11.1%), and unknown (1, 11.1%)." (PMID 38269023, 2023). "The small cell variant is a subtype of ALK-positive ALCL characterized by the coexistence of mainly small tumor cells that stain negative or weakly positive for ALK and CD30, along with a minor population of large tumor cells that stain strongly positive for ALK and CD30." (PMID 38136278, 2023). "The present study clearly provides evidence of a positive correlation between ALK mRNA and protein expression in Em Ca tissues, in contrast to a lack of ALK expression in any of the normal endometrial components, suggesting that ALK overexpression may be a tumor-specific feature of Em Ca." (PMID 37592266, 2023). "Thus, the strength of IL-10RA signaling in ALK+ ALCL affects tumor sensitivity to crizotinib." (PMID 35211406, 2022). "Fifth, we did not have information on tumor genetics which may influence the risk of thrombosis, as some oncogenic rearrangements (for example, ALK or ROS1) are more frequent in patients with adenocarcinoma." (PMID 36077663, 2022). "Moreover, previous evidence has suggested that ALK inhibitors could induce autophagy in tumour cells by inhibiting mTOR phosphorylation, and this autophagy led to cancer cell death." (PMID 35855570, 2022). "However, dynamic circulating tumor DNA (ctDNA) detection of 35 patients receiving ALK‐TKIs of various generations is being conducted in our follow‐up study, which may provide further important information." (PMID 35560808, 2022). "Subsequent identification of ALK rearrangements and several cancer‐driver events, including ROS1, NRG1, NTRK1/RET fusion, BRAF (V600E) mutation, or MET amplification/Exon14 skipping, strengthened the concept of oncogene addiction and tumor heterogeneity as a pillar of modern cancer therapeutics." (PMID 35838331, 2022). "However, spontaneous regression does not occur in older children or in high-risk tumours with characteristics such as MYCN amplification or Anaplastic Lymphoma Kinase (ALK) mutation." (PMID 36263020, 2022). "Furthermore, considering that approximately 30% of tumor biopsy samples may be insufficient to perform ALK characterization, promising data are available on the role of circulating tumor cells as a surrogate to tissue for the detection of ALK alterations." (PMID 35409355, 2022).
tumor (continued). "TLS-related factors, especially their cellular components, were independently protective factors against tumor progression, indicating the potential predominance of humoral immunity in ALK+ tumors, which might help explain the poor efficacy of blocking the PD-1/PD-L1 pathway." (PMID 36233802, 2022). "Some scholars deemed that V3 with more invasive tumor biology presented a worse response to crizotinib, while some findings indicated that patients with V1 had more favorable PFS of crizotinib compared with non‐V119 and other studies suggested V2 had best response to crizotinib among ALK variants." (PMID 34851035, 2022). "Indeed, the presence of ALK alterations could allow them to benefit from an evolving class of anticancer agents that have already demonstrated their efficacy in other tumor types." (PMID 35409355, 2022). "As CD30 and ALK are definitional markers for ALK+ ALCL diagnosis, their evaluation is useful for accurate diagnosis, particularly to highlight the tumor cells of morphologic variants, in which hallmark cells may be scarce or masked by abundant inflammatory infiltrates." (PMID 36010351, 2022). "Furthermore, anti-ALK drugs such as crizotinib, alectinib, and ceritinib may downregulate the STAT3 pathway in pcALCL patients with ALK rearrangements, resulting in tumor cell death." (PMID 35406421, 2022). "Importantly, this effect was independent of genomic ALK alterations making it particularly attractive for tumor types with high ALK protein expression in the absence of ALK-activating mutations or rearrangements, such as NEPC." (PMID 36337169, 2022). "A real-time evaluation of single CTCs complementary to bulk sample analysis (i.e., tumor biopsies and ctDNA) in a larger cohort of patients is needed to confirm the clinical relevance of CTCs in depicting critical genomic events that drive resistance to ALK-TKIs in ALK-positive NSCLC." (PMID 34272470, 2021). "We found that upon combined ALK and autophagy pharmacological inhibition, these drugs had a synergistic effect on the reduction of cell viability; they drove cells towards apoptotic/necrotic cell death, strongly reduced ALK+ Karpas-299 clonogenic survival, and impaired xenograft tumor growth." (PMID 34685497, 2021). "Second, due to the heterogeneity of tumor tissues, most sites in the tumor tissues could not be examined, which greatly affects the accuracy of conventional ALK mutation examination." (PMID 33738250, 2021). "Thus, fusions in ROS1, RET, NTRK1 and amplifications in MET, ALK, EGFR, for example, may not be detected with circulating DNA and RNA, notably during tumor progression under treatment with TKI targeting ALK rearrangements." (PMID 33467720, 2021). "The data published to date suggests that the first-line immunotherapy in monotherapy strategy has become the new standard of care in locally advanced and metastatic NSCLC patients with high PD-L1 expression levels and no EGFR and ALK genomic tumor aberrations targetable mutations." (PMID 34640601, 2021). "While ALK TKIs directly inhibited tumor viability and enhanced antitumor immunity via downregulation of PD-L1, anti-PD-1 antibody was effective in both crizotinib sensitive and resistant cell lines, suggesting the need for further study in anti-PD-1 blockade for treatment of ALK-rearranged NSCLC." (PMID 33806977, 2021). "It is as yet unclear, however, whether ALK-TKI resistant tumor cells that have adopted mesenchymal features develop ALK resistance mutations at the same time, or whether tumor cells with ALK resistance mutations and those undergoing EMT just co-exist in one and the same lesion." (PMID 33572278, 2021). "In addition, the present study found that ALK-positive tumours lack air bronchograms." (PMID 33707479, 2021). "However, mutations in oncogenic drivers such as EGFR, ALK, BRAF, or MET modify the immune tumor microenvironment and may promote anti-PD1/PD-L1 resistance." (PMID 34208111, 2021).
tumor (continued). "However, ALK-positive patients tend not to smoke, have a low tumor mutation load, and have a poor response to PD-1 inhibition." (PMID 34660278, 2021). "For NSCLC in particular, different studies have shown that TMB in the primary tumour tends to be higher in men than in women and is also positively correlated with tobacco consumption, KRAS, and BRAF mutated tumours, whereas the presence of ROS1 and ALK rearrangements is linked to lower TMB." (PMID 34683113, 2021). "Interestingly, ALK staining in CTCs was more homogenous compared to IHC or FISH from the tumor." (PMID 34680298, 2021). "Notably, the ALK L1196M mutation was only observed in tumor lesions with epithelial features, being absent in the mesenchymal ones." (PMID 33572278, 2021). "Besides the secondary mutations in ALK gene, other mechanisms might contribute to tumor resistance to ALK tyrosine kinase inhibitors (ALK-TKIs)." (PMID 34804000, 2021). "Such heterogeneity could impact the clinical interpretation of diagnostic biopsies and may obscure reasons for nonresponse to ALK inhibitor therapy in patients in whom the majority of the tumour cells do not contain activating ALK mutations." (PMID 34815394, 2021). "Adequate tumour samples were obtained from 93.0% (66/71) rebiopsy and 94.0% (126/134) initial biopsy patients for EGFR mutation analysis (p = 0.765), and from 100% (8/8) rebiopsy and 99.1% (122/123) initial biopsy patients for ALK rearrangements analysis (p = 1.000)." (PMID 32907572, 2020). "The perpetual adaptation of tumor cells to ALK-TKIs leading to acquired resistance remains a major challenge in treating ALK fusion positive NSCLC patients, and identification of prognostic biomarkers could help guide treatment choice, as well as sequence of administration." (PMID 32055239, 2020). "Furthermore, we also chose patients with other known off-target tumor-associated SNVs, as not all patients acquire ALK mutations during treatment." (PMID 32290439, 2020). "This change may indicate that ALK TKIs are effective in eliminating ALK rearranged tumor cells." (PMID 32674491, 2020). "The model also failed to incorporate other clinical and pathological prognostic factors (e.g., tumor markers, PET–CT value, and central or peripheral tumor) and some important recognized prognostic molecular factors (e.g., KRAS mutations, EGFR mutations, and ALK rearrangements)." (PMID 31884561, 2020). "Moreover, we cannot exclude the possibility that the canonical and non-canonical ALK fusions could be harbored by different subclones of the same tumor and these subclones could have different ALK TKI sensitivity and oncogenic potentials." (PMID 33363027, 2020). "Notably, in this setting recent studies are focusing on the CSF liquid biopsy as a useful tool in case of massive and rapid progression in order to redefine the biology of the tumor and to overcome the resistance by the switch to another adequate ALK inhibitor." (PMID 33352844, 2020). "While the role of certain targeted therapy is well established in specific tumor types, such as the use of ALK inhibitors in ALK-rearranged non-small cell adenocarcinoma, the efficacy of tissue-agnostic therapy when used off-label and off-clinical trials may not be well characterized." (PMID 32182657, 2020). "The median age in patients with metastasis was even smaller than that (52 years old) in another study neglecting the tumor sites of NSCLC patients, which suggested that ALK mutations could be more prevalent in the metastases instead of in primary tumors for younger patients." (PMID 33488709, 2020). "Finally, we show that chromosome 2p is not frequently gained in tumours with ALK mutations, indicating that mutated ALK alleles are not selected for high expression by copy number gain." (PMID 30778092, 2019).
tumor (continued). "In addition to loss of large regions on chr1p, 3p, and 11q and a broad gain of chr17q, VCF2CNA found frequent focal amplifications of MYCN in NBL tumors and several potential cancer-related CNAs, including high-level amplifications of CDK4 (1 tumor), and ALK (2 tumors)." (PMID 31316100, 2019). "In addition to the relative abundance of EGFR-mutations and ALK-rearrangements, the levels of phosphorylation of EGFR, ALK, or downstream proteins detectable in tumor samples by IHC have been proposed for predicting the efficacy of TKIs in NSCLC with EGFR/ALK co-alterations." (PMID 31266248, 2019). "It is not known whether ALK mutation was present in the original tumor or developed at relapse, however, the patient remained stable for 16 weeks before onset of disease progression." (PMID 31334113, 2019). "Thus, numerous studies have shown that silencing of tumour suppressor genes by DNA methylation could also play a role in aberrant ALK-induced malignant transformation." (PMID 31366041, 2019). "However, no ALK mutations were detected in any of the tumours, in this set, carrying segmental 11q-deletion while in patients without 11q deletion, 20% presented ALK point mutations (n = 27; P value 0.01)." (PMID 30778092, 2019). "Tumours with somatic mutations such as BRAF, EGFR or gene rearrangements such as ALK are considered therapeutic options regardless of tumour type or location, and tumours may even be characterised as BRAFomas or ALKomas." (PMID 30667539, 2019). "We examined whether high PD-L1 expression, tumor mutational burden (TMB), and presence of targetable mutations (EGFR, BRAF, ERBB2, RET or ALK translocations, ROS1 rearrangements) occur at different frequencies in tumors from black patients compared to non-black patients." (PMID 31645901, 2019). "Intra-tumoral clonal heterogeneity, co-existence of the two alterations in the same tumor cells, very rapid acquisition of the co-alteration right after initiating TKI-treatment, or a combination of these circumstances have been envisioned as possible causes of EGFR/ALK co-alteration in NSCLC." (PMID 31266248, 2019). "For patients with EGFR mutation-positive, ALK rearrangement-positive or ROS1 rearrangement positive tumours first-line molecular targeted tyrosine kinase inhibitors are recommended, while patients with high PD-L1 expression in the tumour are suitable for pembrolizumab first-line treatment." (PMID 31088547, 2019). "While MYCN amplification status was available for each tumor sample, ALK mutation status was not." (PMID 30952905, 2019). "In addition, the PD-L1 expression level in tumour cells may also be involved in the objective responses of patients with EGFR+/ALK+ NSCLC." (PMID 31747941, 2019). "Depending on the tumor type, the RAS/MEK/ERK pathway acts alone or cooperates with other oncogenic pathways [e.g., JNK-, PI3K/AKT-, IL-6/STAT3, and echinoderm microtubule associated protein-like 4/anaplastic lymphoma kinase (EML4/ALK)-dependent pathways] in increasing PD-1L." (PMID 31117237, 2019). "However, whether IL-10 secreted by ALK-positive tumor cells affects MHC class II expression in ALCL patients has not been shown directly." (PMID 29642597, 2018). "Also during the last decade, a number of genetic alterations have been described in NSCLC, being Kristen Rat Sarcoma viral oncogene (KRAS), Epidermal Growth Factor Receptor (EGFR) and Anaplastic Lymphoma Kinase (ALK) the most commonly altered oncogenes acting as tumor genomic drivers." (PMID 29455666, 2018). "CHMFL-ALK/EGFR-050 showed potent anti-tumor activity in pre-clinical NSCLC models driven by either mutant EGFR or ALK, but whether or not it will be suitable for NSCLC patients and a less toxic alternative for patients with dual ALK/EGFR overactivity, remains to be determined." (PMID 29455675, 2018).